BCL2 (BCL2 apoptosis regulator)
Diseases named in the same sentence as BCL2 in open-access papers (continued):
Sharing a sentence is not in itself a finding about the gene and the disease.
skin cancer (20 papers, 2014 to 2026). "However, treatment with yeast caused a decrease in Bcl2 expression in a dose-dependent fashion when compared with animal bearing skin cancer alone." (PMID 31098389, 2018). "Bcl-2, an anti-apoptotic protein frequently upregulated in skin cancers, contributes to resistance against programmed cell death." (PMID 39852004, 2025). "The therapeutic utility of DNAzymes has been explored in various disease contexts, including targeting VEGF in age-related macular degeneration, c-Jun in skin cancer, and BCL-2 in hematologic malignancies." (PMID 40643466, 2025). "On the contrary, we have found that apigenin attenuates the expression of proteins recognized as key molecules for skin cancer progression, such as Cyclin D1, Akt and Bcl2, while inducing the cleaving of Caspase 3, which plays a central role in apoptosis." (PMID 35163299, 2022). "B-cell lymphoma-2 (bcl-2) protein and cyclooxygenase 2 (cox-2) protein are known tumour markers, expressed in a variety of tumour cells, including skin cancers, and can be used for the evaluation of the stages of tumour tissue." (PMID 29156646, 2017). "The extract from the UE demonstrated the ability of inhibiting both cancer cell proliferation and metastasis by downregulating the skin tumor-promoting genes such as Bcl-2, STAT3, and MMP-9." (PMID 29065632, 2017). "Over-expression of pro-survival Bcl-2 is common in many types of skin cancers and has been correlated with decreased sensitivity to radiation." (PMID 26148186, 2015). "However, C. quadrangularis extract facilitates apoptosis in A431 skin cancer cells by increasing the Bax/Bcl-2 ratio." (PMID 34203930, 2021). "Therefore, we chose a widely used in vivo model of chemically induced skin cancer in mice to test the effects of our new delivery system using as control parameters bcl-2 and on cox-2 protein expression levels." (PMID 29156646, 2017). "As epidemiological studies also showed that the expression of anti-apoptotic BCL-2 can be higher than the expression of BCL-xL and MCL-1 in skin cancer cells, BH3 mimetic substances are in the focus of research and clinical trials." (PMID 37210688, 2023). "Moreover, altered expression of Bcl2 family member proteins including Bcl2 and Bax in skin tumors as compared to case-matched nonneoplastic skin samples has been observed, clearly suggesting their critical roles in skin carcinogenesis." (PMID 26349906, 2015).
colon adenocarcinoma (19 papers, 2012 to 2024). "In addition, elevated expression of Bcl-2 and deficiency in Bax might cause apoptosis-resistance in colon adenocarcinomas." (PMID 31108984, 2019). "Similar results were also reported in BCS-TC2 human colon adenocarcinoma cells, where resistance to butyrate induces the impairment of the mitochondrial apoptosis pathway through inactivation of Bax and upregulation of Bcl-2." (PMID 34829834, 2021). "Our lab has previously demonstrated that exogenous Reg4 added to human colon adenocarcinoma cells leads to upregulation of the anti-apoptotic gene bcl-2 and induces resistance in vitro to ionizing irradiation and 5-FU chemotherapy." (PMID 33659040, 2021). "Early in this study, expression analysis of apoptotic factors in the panel colon adenocarcinoma cell lines has provided evidence for a notable overexpression of BCL-2 in RKO cell line." (PMID 27520705, 2016). "Moreover, the cytotoxic and pro-apoptotic effects of Bacillus coagulans on COLO205 colon adenocarcinoma cell line was also attributed to increased BAX/Bcl-2 ratio, increased caspase-3 levels and PARP cleavage." (PMID 38258008, 2024). "We report that miR-148a-3p overexpression induced selective CRC cytotoxicity, triggering caspase-3-dependent apoptotic cell death via Bcl-2 downregulation, in line with evidence showing that miR-148a-3p overexpression reduced the progression of colon adenocarcinoma." (PMID 37686618, 2023). "In human colon adenocarcinoma HT-29 cells, ATL I decreases proliferation, accelerated apoptosis, produces DNA fragmentation, and may have anti-colon adenocarcinoma actions through modulating Caspase and Bcl-2 expression in cells." (PMID 37241729, 2023). "The induction of apoptosis by Epo and LFM-A-13 in the cells was confirmed by phosphatidylserine externalization, loss of mitochondrial membrane potential, and modulation of the expression of apoptotic protein BAX and antiapoptotic protein BCL-2 in colon adenocarcinoma cells." (PMID 29690619, 2018).
lymphoid neoplasm (19 papers, 2009 to 2025). A neoplasm composed of a lymphocytic cell population which is usually malignant (clonal) by molecular genetic and/or immunophenotypic analysis. "When combined with the BCL2 oncogene, Arid1a loss indeed promoted progression of lymphoid tumors in mice." (PMID 39843653, 2025). "According to the recent WHO classification of lymphoid neoplasms (2016), HGBLs with c-Myc, Bcl2, and/or Bcl6 rearrangement were classified as double expressors and/or triple expressors, respectively." (PMID 36312606, 2022). "The overexpression of the BCL-2 family anti-apoptotic members, like BCL-2 or BCL-xL has been largely reported in lymphoid tumors but also in AML and other tumors." (PMID 26625317, 2016). "It is well known that over expression of anti-apoptotic Bcl-2 proteins leads to apoptosis-resistance and is believed to be a major reason for treatment failure in lymphoid tumors." (PMID 19220884, 2009). "Among the most common molecular genetic abnormalities in lymphoid tumors are those involving Bcl-2 and other apoptosis-regulating molecules." (PMID 19220884, 2009). "Sequencing of the VHDJH region of the heavy chain (IgH) gene locus (deduced from the transcriptome) showed that both the large B-cell and the plasma cell types of lymphoid expansions were either monoclonal or oligoclonal, thus indicating that the TRAF3/BCL2 double-tg mice develop lymphoid neoplasms." (PMID 30687320, 2018). "Co-expression of MYC with BCL-XL or BCL-2 also influenced the tumor phenotype; Rather than a mixed phenotype of myeloid and T lymphoid tumors, development of an aggressive AML-like disease was favored." (PMID 22393362, 2012). "Markers for lymphoid neoplasms (CD3, CD5, and CD20), cyclin D1, and BCL2 were negative, and EBER in situ hybridization was also negative, effectively excluding lymphoid and viral-driven differentials." (PMID 40951125, 2025).
prostate tumors (19 papers, 2000 to 2024). "The over-expression of bcl-2 can also give a replication capacity to the hormone- resistant prostatic tumor cells, associated with the poor prognosis of this neoplasm." (PMID 11500787, 2001). "Module 3 includes NTRK2, DDR2, and STAT5B, which have been associated with prostate tumor metastasis, and JAZF1, ZEB1, and BCL2, which have been linked to cancer progression and resistance to chemotherapy." (PMID 39347576, 2024). "Gene expression quantification of selected oncogenes and tumor suppressor genes, involved in this pathway showed that KRAS and BCL2 were consistently upregulated in prostate tumor specimen, whereas PTEN was consistently downregulated." (PMID 29268752, 2017). "Bcl-2 is an androgen-regulated oncogene that is overexpressed in a variety of cancers, including androgen-refractory prostate tumors." (PMID 26295410, 2015). "Our study provides rationale for targeting Akt, EGFR, Src, Bcl-2, and AR signaling as a treatment for AR-positive relapsed prostate tumors after hormone therapy." (PMID 24349321, 2013). "Beta-hydroxy-DHP from G. Glabra extract induced Bcl-2 phosphorylation, G2/M cell cycle arrest and apoptosis in breast and prostate tumor cells." (PMID 18955370, 2011). "The specific alternative signaling pathways that allow prostate tumors to bypass AR have been somewhat elusive, one candidate pathway possibly involving BCL2." (PMID 17598908, 2007). "Therefore, targeting the antiapoptotic BCL‐2 proteins is an attractive strategy to lower the apoptotic threshold and increase therapeutic response in prostate tumors." (PMID 31228231, 2019). "In summary, our findings reveals, for the first time, that increased expression and secretion of FAM3B in vivo may play an important role in development and progression of prostate tumors mainly by increasing Bcl-2 and Bcl-XL cell survival genes." (PMID 29357840, 2018). "Similar to observations of AR and IGF-1 expression, levels of the anti-apoptotic protein BCL-2 and the ratio of BCL-2/BAX, a marker of prostate tumor proliferative potential, were higher in animals submitted to the CS protocol than in all other groups." (PMID 32321149, 2020). "Based on the regulatory network analysis of primary prostate tumor, HOXD10, BCL2 and PGR are 3 key elements in the network." (PMID 28005952, 2016). "Analyses of human prostate tumor specimens suggest that PI3K/AKT and MEK/ERK signaling pathways are frequently activated by IGF-1, ErbB2, and VEGF in prostate tumors, via the phosphorylation, subsequent activation of NF-κB, Bcl2 protein, and deactivation of p21 and Bad protein." (PMID 25003983, 2014).
glaucoma (18 papers, 2009 to 2025). Increased pressure in the eyeball due to obstruction of the outflow of aqueous humor. "Axotomy and glaucoma cause apoptosis of RGCs, as has been demonstrated by expression studies of caspases, Bcl-2/Bax and c-jun." (PMID 19473529, 2009). "According to the network analysis and molecular docking simulation, the candidate drug for the in vivo experiment was baicalein, which targeted multiple glaucoma-related targets and had a powerful binding pattern with the apoptosis-related target BCL-2." (PMID 34823561, 2021). "The activation of caspase-3, downregulation of Bcl-2 and upregulation of Bax in a rat model of glaucoma were reversed by AA, indicating that AA inhibits RGC apoptosis by regulating the mitochondrial pathway-related cell death." (PMID 30079010, 2018). "Further studies will be needed to clarify the molecular mechanism among OPA1, Bax, and Bcl-2 in experimental glaucoma." (PMID 30323741, 2018). "In glaucoma, the decreased expression of the pro-survival bcl-2 and bcl-xl genes is accompanied by an increase in pro-apoptotic bax and bad gene expression." (PMID 30524222, 2018). "The Bcl-2-related apoptotic pathway is activated and participates in the pathogenesis of several RP diseases as well as in glaucoma, retinal ischemia and retinal detachment." (PMID 19672311, 2009). "While expression of Bax is upregulated following ischemia-induced retinal injury in rat, concomitant decreased Bcl-2 and increased Bax protein levels have been reported after elevated intraocular pressure in murine glaucoma model." (PMID 19672311, 2009). "Bcl-2 has also been assessed in the experimental model of glaucoma after hypertonic saline injection." (PMID 19862336, 2009). "In fact, p75 NTR mRNA expression increases in retina during experimental glaucoma starting at 20 days, corresponding to increased Bcl-2/Bax ratio and apoptotic cell death." (PMID 19473529, 2009). "Gamma-synuclein can be considered a member of the Bcl-2 apoptosis family, and its overexpression participates in the pathogenesis of glaucoma by facilitating the disintegration of neurofilament networks, by activating astrocyte phagocytosis in the ONH and inhibiting the optic nerve regeneration." (PMID 41515932, 2025). "Similarly, investigations have revealed a stronger expression of the pro-apoptotic Bax protein in the optic nerve axons of glaucoma patients in comparison to the anti-apoptotic Bcl-2 protein." (PMID 39881870, 2024). "These protective effects of baicalein on glaucoma damage might be related to the activation of BCL-2 expression, decreasing of apoptotic cells in the GCL." (PMID 34823561, 2021). "I have elucidated how BCL-2 serves an anti-inflammatory function through inhibiting the transcription factor NF-kB and how activation of NF-kB has been linked to AMD, cataractogenesis and glaucoma." (PMID 30857240, 2019). "The BCL-2 (B-cell lymphoma-2) family of proteins contributes to mitochondrial-based apoptosis in models of neurodegeneration, including glaucomatous optic neuropathy (glaucoma), which degrades the retinal ganglion cell (RGC) axonal projection to the visual brain." (PMID 34984584, 2022). "BAX, the pro-apoptotic BCL2 member required for the normal death of RGC during development, has been identified as a major mediator of RGC death in glaucoma." (PMID 24736625, 2014). "The therapeutic effects of baicalein on glaucoma might be related to reduced apoptosis in GCL and up-regulated the expression of BCL-2 in a COH rat model, at least partially verifying the predicted consequences of network pharmacology." (PMID 34823561, 2021).
glaucoma (continued). "Therefore, BCL2 or other Bcl-2 family proteins may be critical in maintaining somal survival, somal health, and axonal degeneration, and MKK4/7-mediated inhibition of Bcl-2 family proteins may contribute to RGC degeneration in glaucoma." (PMID 41397991, 2025).
Hypertension (18 papers, 2014 to 2025). The presence of chronic increased pressure in the systemic arterial system. "PPI network analysis revealed three potential key targets—MMP9, HIF1A, and BCL2—that are significantly implicated in the treatment of hypertension with catechins." (PMID 39272451, 2024). "Therefore, MMP9, HIF1A, and BCL2 are closely linked to the onset and progression of hypertension, and catechin components may deliver their anti-hypertensive benefits through interactions with these target proteins." (PMID 39272451, 2024). "Four studies analyzed the effect of exercise training on Bcl-2 in hypertension and showed similar results." (PMID 37187789, 2023). "We evaluated the intrinsic pathway of apoptosis and noticed that arterial hypertension generated an increase in the antiapoptotic protein BCL-2 and a decrease in the proapoptotic protein BAX and consequently considerably decreased the BAX/BCL-2 ratio." (PMID 36865350, 2023). "Our group demonstrated that moderate or intense resistance or aerobic exercise promotes alteration in urogenital apoptosis, increasing BAX and reducing BCL-2, even if the animals are submitted to high-fat diets or have arterial hypertension." (PMID 36865350, 2023). "Most interestingly, we found that exercise reversed hypertension-induced elevation in the Bax/Bcl-2 ratio and activated caspase-3, supporting the protective effects of continuous aerobic exercise against increased apoptosis." (PMID 35898283, 2022). "We identified that EGCG treatment activated the Bcl-2 family-related pro-survival pathway against early aged hypertension in the cerebral cortex, as evidenced by the up-regulated levels of Bcl-2, Bcl-xL, pBad, and 14-3-3." (PMID 34456710, 2021). "Higher Bcl-2-to-Bax ratios due to the upregulation of Bcl-2 and/or downregulation of Bax expression are commonly found in VSMCs of hypertension." (PMID 27455221, 2016). "Further, it has been reported that Losartan has relevance on Bax and Bcl-2 expression in hypertension." (PMID 24796787, 2014). "However, hypertension-induced Bcl-2 protein expression was profoundly suppressed by QXJYD treatment." (PMID 27455221, 2016). "CG, GCG, ECG, and EGCG were identified as key catechin components for combating hypertension, with MMP9, HIF1A, and BCL2 as potential critical therapeutic targets." (PMID 39272451, 2024). "However, Bcl-2 was related to hypertension and glomerular hypertrophy, which could develop CKD." (PMID 36699321, 2022). "Combined with protein interaction network analysis, the potential primary targets of berberine in treating hypertension may include AKT1, BCL2, EGFR, STAT3, and TNF." (PMID 41567631, 2025). "In presented study, we demonstrated that hyperbaric oxygen preconditioning increased pro-apoptotic Bax as well as anti-apoptotic Bcl-2 protein, measured 24 h after ischemic insult in rats with and without hypertension." (PMID 33573145, 2021). "On the other hand, in Ang II induced-hypertension, Losartan reduced the expression of Bax in the kidney, but did not affect Bcl-2 level." (PMID 24796787, 2014). "The BAX/BCL-2 ratio was decreased in the SHRc group, perceived as a reflection of the imbalance generated by arterial hypertension; thus, the SHR+T group presented increases in this ratio through regulation of the imbalance generated by hypertension (p = 0.033)." (PMID 36865350, 2023). "The levels of cleaved-caspase 3/caspase 3, cleaved-caspase 8/caspase 8, Bax/Bcl2, LC3 II/LC3 I, Beclin-1 and autophagy related 7 (ATG7) were increased in the heart of HSD rats with hypertension (HTN), and in hypertension-prone (HP) and hypertension-resistant (HR) rats." (PMID 33996809, 2021). "Furthermore, the included studies reported that exercise training increased the levels of Bcl-2, Akt, p-Akt, PI3K, p-PI3K, IGF-1, and HSP 72 cardiac tissue in hypertension, suggesting that exercise training increases the chances of cell survival in the cardiac tissue to counteract hypertension." (PMID 37187789, 2023).
Hypertension (continued). "This study showed that HBO preconditioning increased expression of the anti-apoptotic Bcl-2 protein, after induction of postischemic AKI in rats with and without hypertension." (PMID 33573145, 2021).